RN7SL37P (RNA, 7SL, cytoplasmic 37, pseudogene)
Gene: Miscellaneous RNA gene on chromosome 5 (37,246,173 to 37,246,479, reverse strand). Ensembl gene ENSG00000242493.
Homologues: Orthologues: chimpanzee Metazoa_SRP (99% identical), macaque Metazoa_SRP (85% identical). Paralogues in human: RN7SL1 (79% identical), RN7SL2 (78% identical), RN7SL3 (78% identical), RN7SL7P (78% identical), Metazoa_SRP (77% identical), RN7SL627P (77% identical), Metazoa_SRP (76% identical), RN7SL714P (76% identical), RN7SL788P (76% identical), RN7SL45P (76% identical), RN7SL127P (76% identical), RN7SL296P (76% identical), and 700 more.